SLC7A11 (solute carrier family 7 member 11)
Diseases named in the same sentence as SLC7A11 in open-access papers (continued):
Sharing a sentence is not in itself a finding about the gene and the disease.
tumor (continued). "This is in line with previous reports where blocking Slc7a11 by the pharmacological agent, erastin, was shown to deplete GSH levels and mediate the stress response in immortalized tumor cell lines resulting in ferroptosis." (PMID 38757355, 2024). "These interferences in the SLC7A11-GSH-GPX4 signaling axis, paired with imbalances in iron homeostasis, were shown to greatly heighten ferroptosis in tumor cells, as corroborated by both in vitro and in vivo evidence." (PMID 38505601, 2024). "It was also recently determined that CTLs secrete IFNγ to activate the STAT1-IRF1 axis, in order to repress the expression of SLC7A11 and SLC3A2 to induce the extrinsic ferroptosis pathway in tumor cells." (PMID 36672246, 2023). "The study further reported the activity of SLC7A11 and GPX4 in combination with ferroptosis inducers to cervical cancer in vitro and in vivo experiments, and found that tumor cells were considerably more sensitive to radiotherapy." (PMID 37025659, 2023). "Colorectal sections of the mice (a tumor-prone site) were examined by immunohistochemistry (IHC) staining and iron-specific staining (Prussian blue) for the key proteins CD44 and SLC7A11." (PMID 36672372, 2023). "Deletion of SLC7A11, a cystine-glutamine anti-transporter, decreased cystine import, downregulated GSH activity, and induced tumor ferroptosis." (PMID 36768241, 2023). "KRAS-mutant LUAD cells express high levels of SLC7A11 and GPX4; pharmacological or genetic inhibition of either SLC7A11 and GPX4 attenuates tumor growth in vivo." (PMID 37161053, 2023). "Before and after the treatment of QLD, we measured several ferroptosis-related biomarkers (SLC7A11, SLC3A2, GPX4, and FSP1) in tumor tissues from the patients with CRPC." (PMID 37576395, 2023). "Overexpression of miR-27a can negatively regulate SLC7A11 protein and intracellular GSH levels, which leads to the re-sensitization of drug-resistant tumor cells." (PMID 36936418, 2023). "The SLC7A11 inhibitors sulfasalazine and erastin, and the GPX4 inhibitor RSL3, suppress tumor growth in vitro and in vivo." (PMID 37381723, 2023). "IHC images showed that the positive staining patterns for SLC7A11 and GPX4 were observed in the cell membrane of tumour tissues." (PMID 37807410, 2023). "SLC7A11 protein was positively expressed in 78 tumour tissues, but only 37 in normal tissues; meanwhile, GPX4 protein was positively expressed in 72 tumour tissues, while only 33 cases exhibited positive staining in normal tissues." (PMID 37807410, 2023). "Our results on drug sensitivity analysis demonstrate a strong correlation between the expression of the SLC7A11 gene and the sensitivity of ACC patients to anti-tumor drugs." (PMID 37919768, 2023). "STAT1 then upregulates IRF1 to repress the expression of SLC7A11 and SLC3A2, the two subunits of the glutamate-cystine antiporter system xc-, to limit tumor cell cystine uptake, resulting in tumor cell lipid peroxidation and death." (PMID 36672246, 2023). "Pharmacologic inhibitors of xCT (either SLC7A11 or GPX4) induce ferroptosis of NSCLC cells and other tumor types." (PMID 37381723, 2023). "In the tumour microenvironment, CD8 (+) T cells produce IFN-γ, downregulating SLC7A11 expression, reducing cystine uptake, fostering lipid peroxide accumulation, and inducing ferroptosis in Melanoma and ovarian cancer cells." (PMID 38273826, 2023). "It has been confirmed that the regulation of the glutamate/cysteine reverse transport system key proteins can affect ferroptosis in tumor cells, such as SLC38A1, SLC1A5, SLC3A2, and SLC7A11." (PMID 37369681, 2023).
tumor (continued). "This circP4HB/miR-1184/SLC7A11 axis protects LUAD from erastin-induced ferroptosis and promotes tumor growth in vivo and in vitro." (PMID 37834062, 2023). "MSCPF can inhibit the expression of SLC7A11, GPX4, and P-gp, thereby enhancing the accumulation of sorafenib in tumor cells and improving the antitumor effect." (PMID 37894410, 2023). "A study found that SLC7A11 abrogation tremendously decreased tumor growth and CAF activation in vitro and in vivo, making targeting SLC7A11 treatment in PDAC-derived CAF a potential therapy." (PMID 37784082, 2023). "Many types of cancer cells have an elevated expression of SLC7A11 and SLC3A2, a feature benefiting L-Cystine uptake and high metabolic activity for tumor growth." (PMID 36672226, 2023). "Obviously, XK-81 decreased the protein expression of SLC7A11 and GPX4 in tumor tissues, hinting at the occurrence of ferroptosis." (PMID 37513222, 2023). "Based on the TCGA database, we compared the mRNA expression of PDIA4, ATF4, SLC7A11, and PERK between RCC tumor and adjacent normal tissue." (PMID 36906674, 2023). "Sorafenib (SOR), a frontline drug for the treatment of HCC, induces ferroptosis by inhibiting the Solute Carrier family 7 member 11 (SLC7A11), with inadequate ferroptosis notably contributing to SOR resistance in tumor cells." (PMID 37391845, 2023). "The combination of radiotherapy and immunotherapy downregulates SLC7A11 gene expression, mediated by ATM and IFN-γ induced by DNA damage, resulting in reduced cysteine intake, increased ferroptosis, and enhanced tumor control." (PMID 38562992, 2023). "Interferon-γ from CD8+ T cells can impair tumor cystine uptake by downregulating SLC3A2 and SLC7A11." (PMID 37714846, 2023). "In prostate cancer, liver cancer, and gastric cancer; OSCC, melanoma, and bladder cancer; and nasopharyngeal and other cancers, SLC7A11 increases GSH levels, resists iron-related death, and promotes tumour cell metastasis respectively." (PMID 37829798, 2023). "Consistent with those within the in-vitro experiments, knockdown of COL12A1 in GC cells reduced the tumor mass growth and decreased the expression of GPX4 and SLC7A11 in xenograft models." (PMID 37700383, 2023). "SLC7A11, as a key repressor of ferroptosis, is upregulated in tumors and can interact with ALOX12 to promote tumor progression." (PMID 36846713, 2023). "Studies have shown that m6A methylation regulates lipid peroxidation and ferroptosis through the ferroptosis defence system Xc−, comprising 2 subunits, SLC7A11 and SLC3A4, and a key enzyme of lipid metabolism, ACSL4, which induces ferroptosis in tumours." (PMID 36859310, 2023). "This leads to the elevated transcription of solute carrier family 7 member 11 (SLC7A11) in PCa cells, finally improving the survival of tumor cells." (PMID 37662915, 2023). "Bioinformatical analyses based on clinical tumor samples and database indicated a positive correlation exists between PDIA4 and PERK/ATF4/SLC7A11 signaling pathway, as well as the malignant prognosis of RCCs." (PMID 36906674, 2023). "Therefore, inhibiting SLC7A11 may be a promising target for tumour immune therapy." (PMID 37880315, 2023). "These molecules inhibit the expression of Solute Carrier Family 7 Member 11 (SLC7A11) and Solute Carrier Family 3 Member 2 (SLC3A2), two subunits of the xc system, and further direct the target (tumor) cell toward ferroptosis." (PMID 38139106, 2023). "SLC7A11 and GPX4, which are upregulated in tumor cells, serve to protect them from ferroptosis induced by irradiation." (PMID 37980334, 2023). "In colon cancer cells, tumor-derived H2S, produced mainly by CBS, inhibits ferroptosis by stabilizing SLC7A11 via sulfhydration at cysteine 9133." (PMID 37381723, 2023). "Therefore, the impact of SLC7A11 on tumour immune cells may be very complex." (PMID 37880315, 2023). "Meanwhile, the expression level of SLC7A11 and GPX4 was correlated with tumour diameter and distant metastasis (P<0.05)." (PMID 37807410, 2023).
tumor (continued). "In patient RNA sequencing data, SLC7A11, NQO1, NFE2L2 and GCLM gene expression was higher in CRUK0772 tumour regions compared to CRUK0640." (PMID 38168428, 2023). "IHC testing revealed that SLC7A11 expression decreased and lipid peroxide 4‐hydroxynonenal (4‐HNE) increased in the tumor samples of the sh‐DUXAP8 group, and a positive correlation was observed between SLC7A11 and 4‐HNE levels." (PMID 37337470, 2023). "This eventually results in the inhibition of the SLC7A11/GPX4 axis and the promotion of ferroptosis in various tumor cells." (PMID 38081931, 2023). "Thus, the targeted inhibition of CD44/SLC7A11 may make tumor cells prone to ferroptosis." (PMID 36672372, 2023). "However, our studies also revealed that high overexpression of SLC7A11 suppressed tumor metastasis, and CTCs exhibited lower SLC7A11 expression than did primary tumor samples from patients, which may seem counterintuitive in light of SLC7A11’s established tumor-promoting effect." (PMID 37339981, 2023). "Administration of 65 (10 mg/kg, ip) to mice with grafted MDA‐MB‐231 cells accordingly reduced the tumor burden, and cotreatment with 14 (200 mg/kg) prevented the upregulation of KFL4 and SLC7A11 and exhibited superior antitumoral activity." (PMID 36658724, 2023). "In pancreatic ductal adenocarcinomas (PDACs), overexpressing SLC7A11 inhibits ferroptosis by increasing cystine uptake and GSH production, promoting tumour growth." (PMID 38273826, 2023). "We analyzed the expression of genes in tumor and normal samples, and the results showed that NDUFS1, NDUFS2, NDUFC1, and EPAS1 were downregulated in CRC, and SLC7A11, OXSM, LRPPRC, NDIFA11, NUBPL, and CONT1 were upregulated in CRC." (PMID 37978247, 2023). "Tumor cells produce glutamate, which is released through the SLC7A11 (solute carrier family 7 member 11) glutamate–cysteine exchanger." (PMID 35875065, 2022). "For example, the expression of SLC7A11, FANCD2, and CISD1 was higher in tumor tissues than that in normal tissues, but ATP5MC3 was lower." (PMID 35309947, 2022). "It is thought that the release of glutamate from the tumor microenvironment (TME) via a cystine-glutamate exchanger (SLC7A11, xCT) contributes to this clinical presentation." (PMID 35350689, 2022). "SLC7A11-dependent cystine import led to sufficient GSH synthesis and lipid peroxidation inhibition, thus accelerating tumor growth." (PMID 35884471, 2022). "Subsequent overexpression experiments demonstrated that MITD1 knockdown induced ferroptosis and suppressed tumor growth and migration through the TAZ/SLC7A11 pathway." (PMID 36046690, 2022). "IFN γ released from immunotherapy-actived CD8+ T promotes ferroptosis in tumor cells by decreasing the expression of SLC3A2 and SLC7A11, which is instrumental in boosting the efficacy of cancer immunotherapy." (PMID 35309911, 2022). "SLC7A11 promotes the absorption of Cys2, which in turn supports GSH synthesis and inhibits ferroptosis in tumor cells." (PMID 36072803, 2022). "The results of immunohistochemical staining showed that the expression levels of KI67, GPX4, SLC7A11, and TET1 in the tumor tissues of NOD-scd mice injected with Atranorin@SPION were significantly lower than those in the control group." (PMID 36237989, 2022). "Western blotting of tumor tissues showed that the expression levels of GPX4 and SLC7A11 were downregulated after treatment with apatinib." (PMID 35602105, 2022). "Thus, our findings suggested SLC7A11 may play a functional role in tumor metastasis." (PMID 35509981, 2022).
tumor (continued). "Here, we identified a Uc.339/miR-339/SLC7A11 axis that involves LncRNA T-UCR Uc.339-mediated repression of miR-339 and affects the expression of SLC7A11 to participate in tumor metastasis and development." (PMID 35399708, 2022). "Together with the affinities of YY1 and YY2 to SLC7A11 promoter, which also need to be elucidated, the change in YY1 and YY2 levels is crucial for the overall outcome of the ferroptosis level in tumor." (PMID 35246964, 2022). "The IFNγ secreted by CD8+ T cells downregulates the expression of SLC7A11 and SLC3A2, and therefore attenuates the uptake of cystine by tumor cells, consequently enhancing lipid peroxidation in tumor cells, ultimately increasing ferroptosis." (PMID 35531466, 2022). "Then, expressions of OTUB1, SLC7A11 and GPX4 in tumor (n=179) and normal (n=171) tissues as well as their associations with survival outcomes were evaluated." (PMID 35494004, 2022). "In tumor microenvironment, the released IFNγ from CD8(+) T cells suppresses SLC3A2 and SLC7A11 expression on cancer cells, consequently facilitates cancer cell accumulation of lipid peroxidation and ferroptosis." (PMID 36289191, 2022). "The combination of the anti-inflammatory drug ibuprofen and the SLC7A11 inhibitor SASP with chemotherapy showed better efficacy, with obvious growth delay of 3-methylcholanthrene (3-MCA) sarcoma, decreased tumour volume, and improved survival rate in mice." (PMID 35804831, 2022). "Overall, these results indicate that mutations in the YY2 zinc‐finger domains as found in clinical tumor patients abrogated the YY2/SLC7A11 axis, and consequently, abrogated the effect of YY2 on tumor cell ferroptosis." (PMID 35246964, 2022). "CD8(+) T cells promote lipid peroxidation and ferroptosis by inhibiting the expression of SLC7A11 and SLC3A2 transporters by releasing interferon γ and reducing cystine uptake by tumor cells." (PMID 35459272, 2022). "The majority of tumor cells acquire cysteine primarily utilizing system xc- with a transporter submit, the solute carrier family 7 member 11 (SLC7A11, also termed xCT)." (PMID 36335094, 2022). "The tumour stem cell molecules CD44 and OTU deubiquitinase ubiquitin aldehyde binding 1 (OTUB1) were beneficial to the stability of SLC7A11 on the cell membrane, and inhibited the proteasomal degradation of SLC7A11." (PMID 35804831, 2022). "Sorafenib can resist tumor by inhibiting the expression of CD31, alphaSMA, pERK, VEGF, PDGF, TNFalpha, eNOS and HIF-1α/SLC7A11, BRAF/MAPK signaling pathways." (PMID 36544713, 2022). "To further clarify the role of lncRNA HEPFAL and SLC7A11 in HCC, we collected tumor and normal tissue samples from 60 HCC patients at WMU hospital." (PMID 36008384, 2022). "A number of studies have shown that inhibiting SLC7A11, GPX4 or other ferroptosis related molecules can reduce the production of glutathione, thereby promoting tumor cell ferroptosis and suppressing tumor growth and metastasis." (PMID 35579738, 2022). "Another study noted that CD8+ T cells suppress cystine uptake by tumor cells through down-regulation of SLC3A2 and SLC7A11 expression and promote ferroptosis and lipid peroxidation in tumor cells." (PMID 36776357, 2022). "We here develop a novel cancer therapy named Ferroptosis ASsassinates Tumor (FAST) by combining iron oxide nanoparticles with cancer-selective knockdown of seven key ferroptosis-resistant genes (FPN, LCN2, FTH1, FSP1, GPX4, SLC7A11, NRF2)." (PMID 36329436, 2022).
tumor (continued). "Subsequent western blotting analysis showed that IFN-γ markedly reduced tumor cells’ SLC3A2 and SLC7A11 protein expression with increased IRF1 expression, which indicated the possible involvement of the JAK/STAT1 signaling pathway." (PMID 35399527, 2022). "Based on these deductions, we here knock down five additional genes related to iron and redox homeostasis (NRF2, GPX4, SLC7A11, FSP1, FTH1), for further improving the anti-tumor efficacy of GIFT." (PMID 36329436, 2022). "With the ability to import cysteine from and export glutamate into the extracellular environment, SLC7A11 can exert effects on the interplay with cancer cells and TME, which in turn influence tumor growth and response to cancer therapies." (PMID 34796174, 2021). "In many cancer cells, SLC7A11 is adaptively upregulated to alleviate the stress imposed by intracellular ROS and promote GSH synthesis and resistance to ferroptosis, promote tumor growth by inhibiting ferroptosis, and resist resistance to anticancer therapy." (PMID 35360452, 2021). "In support of these results and importantly, analysis of the TCGA and SU2C PC tumor datasets demonstrated that MUC1 significantly correlates with activation of the NFE2L2.V2 signature and SLC7A11 and G6PD gene expression." (PMID 34163028, 2021). "SLC7A11 and SLC3A2 are highly expressed in tumor cell lines and increase cellular antioxidant capacity." (PMID 34630843, 2021). "Moreover, erastin or SLC7A11 depletion to enhance ferroptosis were insufficient to induce macrophage ferroptosis, implicating the considerable role of TAMs against T cell induced-anti-tumor response and the substantial benefit of depleting TAMs for T cell immunotherapy." (PMID 34496935, 2021). "The pan-cancer expression profiles of SLC7A11, HMOX1, and MT1G were subsequently analyzed by integrating tumor samples in TCGA with normal samples in GTEx using the rank-sum test." (PMID 35360452, 2021). "Another tumour suppressor gene-BAP1 can reduce GSH synthesis and induce ferroptosis by suppressing the level of H2A-K119ub on the SLC7A11 gene and the transcription of its mRNA, thereby inhibiting the ability of SLC7A11 to transport cysteine into the cell." (PMID 34912804, 2021). "The UFMylation of SLC7A11 is detected by immunoprecipitation and the expression of UFM1 and SLC7A11 in tumor tissues was detected by immunohistochemical staining." (PMID 34162423, 2021). "Genes which were not only expressed differently between tumor and normal tissue but also of prognostic value were SQLE, SLC7A11 and CHAC." (PMID 33672990, 2021). "The expression of METTL14, SLC7A11 and COX2 in xenografts tumour sections was further investigated by immunohistochemistry." (PMID 34609072, 2021). "To further explore our findings in a clinically relevant setting, we analyzed the hLcn-2-dependent target genes SLC7A11, GCLM, and GLS at mRNA level in either tumor tissue or adjacent healthy tissue of 32 patients diagnosed with clear cell RCC (ccRCC)." (PMID 34069743, 2021). "IFN-γ can downregulate the expression of two subunits of the glutamate-cystine antiporter on the surface of tumor cells, namely, solute carrier family 3 member 2 (SLC3A2) and SLC7A11, thereby inhibiting tumors." (PMID 34335679, 2021). "In murine pancreatic cancer cells, deletion of SLC7A11 was sufficient to decrease cystine import, downregulate GSH activity, and induce tumor ferroptosis." (PMID 34830482, 2021). "CD8+ T cells enhance ferroptosis of tumor cells through releasing interferon gamma (IFNγ) and repressing the expression of SLC3A2 and SLC7A11 in tumor cells." (PMID 34733403, 2021). "Upregulated expression of SLC7A11 (10/14), SLC1A5 (7/14), SLC7A5 (6/14), and SLC3A2 (5/14) was observed in most of the tumor tissues; however, GLS in LUSC, KIRC, and KICH and GLS2 in KIRC and LIHC, were significantly downregulated." (PMID 34573287, 2021).